MPO (myeloperoxidase)
Diseases named in the same sentence as MPO in open-access papers (continued):
Sharing a sentence is not in itself a finding about the gene and the disease.
endothelial dysfunction (continued). "Myeloperoxidase (MPO) level in the blood can be considered as a marker of endothelial dysfunction and could be a predictor of cardiovascular disease risk." (PMID 26379476, 2015). "It was also hypothesized that the MPO−/− animals would be less susceptible to endothelial dysfunction if challenged by LPS." (PMID 24707472, 2014). "Interleukin-2 (IL-2) has been recently proposed as a predictor of HFpEF development, playing a hypothesized role in chronic microvascular inflammation, while neutrophilic myeloperoxidase (MPO)-related oxidative stress has been associated with endothelial dysfunction in HFpEF." (PMID 39062871, 2024). "Notably, MPO+ cluster density was particularly associated with balloon-induced IH of rat aortas, increased amounts of the immune cells in the tunica adventitia, and was augmented at endothelial dysfunction in this experimental model." (PMID 36293013, 2022). "One of the most important pathogenic pathways involving MPO might be endothelial dysfunction." (PMID 28704420, 2017). "Among them, the direct effects of NETs on endothelial dysfunction mainly involve DNA, histones, myeloperoxidase (MPO), matrix metalloproteinases (MMPs), serine proteases, and antibacterial peptide LL37 in NETs." (PMID 40053030, 2025). "Some studies illustrated the link between oxidative stress and endothelial dysfunction by showing the increase in serum levels of markers including Myeloperoxidase (MPO), ICAM-1, VCAM-1, L-selectin, and P-selectin in OSA patients." (PMID 40688196, 2025). "MPO and its byproducts promote processes like foam cell formation, endothelial dysfunction, and MMP‐8 activation." (PMID 38852177, 2025). "A dietary-induced obesity (DIO) and genetically inherited obesity (GIO) mouse model were implemented to study the involvement of MPO in obesity-related endothelial dysfunction." (PMID 40252642, 2025). "Neutrophils act as early responders, releasing reactive oxygen species via NADPH oxidase and myeloperoxidase, modifying leukocyte adhesion and promoting endothelial dysfunction." (PMID 41583468, 2025). "Niacin can significantly reduce the release of MPO from leukocytes, improve endothelial dysfunction, and prevent HDL dysfunction." (PMID 40004147, 2025). "Although MPO and markers of endothelial dysfunction (sICAM-1, sVCAM-1, sE-selectin) were often elevated, they were not consistently associated with clinical endpoints such as myocardial infarction or impaired FMD." (PMID 41226326, 2025). "MPO inhibits adipocyte beiging as a protective mechanism from obesity-induced endothelial dysfunction and furthermore fosters immune cell frequency, ROS formation, and pro-inflammatory cytokine production." (PMID 40252642, 2025). "The data extracted from the included studies present contradicting findings when looking at a less than 3-year duration of exposure to HAART in modulating MPO-related endothelial dysfunction, warranting further research to confirm these findings." (PMID 41226326, 2025). "MPO plays a significant role in AF progression by promoting oxidative stress, inflammation, endothelial dysfunction, and atrial structural remodeling." (PMID 39651434, 2024). "MPO can also play a key role in the regulation of vascular function by limiting the bioavailability of nitric oxide (NO), exacerbating endothelial dysfunction and cardiovascular disease development." (PMID 39087342, 2024). "The oxidation of ROS substrates such as nitric oxide (NO) and protein and lipid components in the vascular endothelium serves as important mechanisms of MPO-mediated endothelial dysfunction." (PMID 37594719, 2024). "MPO contributes to the formation and destabilization of atherosclerotic plaques by oxidizing lipoproteins and promoting endothelial dysfunction, leading to plaque vulnerability and rupture." (PMID 39273041, 2024). "Pre-clinical studies provide additional evidence of a role for MPO as a mediator of endothelial dysfunction." (PMID 39061857, 2024).
endothelial dysfunction (continued). "On the other hand, myeloperoxidase, which is secreted by azurophil granules as well as a DAMP, has been suggested to be implicated in endothelial dysfunction by decreasing the availability of nitric oxide in endothelial cells." (PMID 38921266, 2024). "In this study, the expression of endothelial dysfunction biomarkers such as vWF and ET-1, and CD11b and MPO double positive cells increased when lung strain reached 1.5, indicating that the UPLS provoked the inflammation." (PMID 39845800, 2024). "Neutrophil extracellular traps, for the release of which, myeloperoxidase is a significant contributor, have been demonstrated to contribute to inflammation and endothelial dysfunction." (PMID 39407935, 2024). "These cells produce myeloperoxidase (MPO), an enzyme that is significantly elevated in AFD patients and is closely associated with endothelial dysfunction and increased cardiovascular risk." (PMID 39125842, 2024). "In an in vitro experiment, MPO induced endothelial dysfunction by decreasing eNOS Ser1177 phosphorylation." (PMID 38275657, 2024). "Myeloperoxidase (MPO), generated by activated neutrophils, also produces oxidants that scavenge NO, further contributing to endothelial dysfunction." (PMID 38001830, 2023). "Further, quercetin inhibits endothelial dysfunction in AS by reducing HOCl production by MPO/NADPH oxidase." (PMID 37077636, 2023). "Serum nitrite and plasma myeloperoxidase (MPO) levels were measured as biomarkers for endothelial dysfunction and small vessel disease determination." (PMID 37375775, 2023). "Myeloperoxidase is involved in chronic inflammatory conditions and also promotes additional endothelial dysfunction leading to tissue injury through the production of oxidants, thus forming lipid and protein reactive species." (PMID 36767947, 2023). "ROS scavenger (NAC) supplementation or MPO inhibition are potential therapeutic options to reverse the devastating endothelial dysfunction in chronic anemia." (PMID 37234375, 2023). "Flow-mediated dilation (FMD) and reactive hyperemia index (RHI) were used to assess endothelial dysfunction, and we assayed high-sensitivity C-reactive protein, interleukin-6, fibrinogen, p-selectin, and myeloperoxidase as serum measures of inflammation." (PMID 37305426, 2023). "MPO activation is involved in endothelial dysfunction, reduced NO availability, and impaired vasoreactivity leading to cardiovascular disease." (PMID 38034546, 2023). "Of note, HOCl and HOSCN are considered as the key MPO-derived oxidative stress species in endothelial dysfunction and stroke-related thrombosis." (PMID 36439687, 2022). "In concert with these findings, both adventitial and perivascular MPO+ clusters increased in number and were enlarged at endothelial dysfunction triggered by regular injections of CPPs." (PMID 36293013, 2022). "MPO plays an essential part in endothelial dysfunction as well as in platelets activation, indicating its potential role in stroke-related thrombosis." (PMID 36439687, 2022). "MPO and MPO-derived oxidants can not only promote inflammation and lead to tissue damage, but also increase endothelial dysfunction through the production of HCIO to induce vascular permeability and promote the development of RA." (PMID 35740050, 2022). "Collectively, enlarged VV and increased MPO+ clusters in aortas exposed to CPPs in addition to the existing balloon injury suggested a putative role of endothelial dysfunction in the development of VV networks and adventitial/perivascular inflammation." (PMID 36293013, 2022). "MPO released from monocytes was thought to contribute to endothelial dysfunction by limiting nitric oxide (NO) bioavailability via formation of reactive oxidants including hypochlorous acid (HOCl)." (PMID 36180886, 2022).
endothelial dysfunction (continued). "Oxidative stress is another mechanism that is decisive for endothelial dysfunction in chronic kidney disease: the interconnection between these two processes comes through increased levels of myeloperoxidase (MPO)." (PMID 36499242, 2022). "Inflammation and endothelial dysfunction are characteristics of preeclampsia, and increased MPO levels in placental and peripheral circulation in preeclamptic women have been described." (PMID 34737733, 2021). "Once released by PMNs, free MPO can bind vascular ECs and contribute to endothelial dysfunction by limiting NO bioavailability or via HOCl-mediated modification of L-arginine." (PMID 33959129, 2021). "Myocardial reperfusion injury is a dynamic injury with peak myeloperoxidase (MPO) activity and endothelial dysfunction at 24 h." (PMID 32121587, 2020). "For example, pharmacological inhibition of MPO with the analog AZM198 has been identified as a potential strategy to limit endothelial dysfunction." (PMID 33041796, 2020). "The elevation of serum myeloperoxidase (MPO) from activated myeloid cells is associated with increased cardiovascular risk through lipid oxidation, induction of endothelial dysfunction, and release of IL-12 from macrophages." (PMID 33262910, 2020). "Enhanced MPO plasma levels probably decrease the bioavailability of nitric oxide, and can thus promote endothelial dysfunction." (PMID 33137905, 2020). "Released by circulating phagocytes, MPO contributes to endothelial dysfunction by limiting NO bioavailability through formation of reactive oxidants." (PMID 31450823, 2019). "Our ex vivo data show that MPO uptake in porcine coronary artery was augmented by treatment with free fatty acids, which have been shown to promote endothelial dysfunction." (PMID 29572498, 2018). "Although ample evidence indicates that MPO-derived oxidants play an important role in endothelial dysfunction physiological relevance of 2-ClHA-induced BMVEC dysfunction is a major question arising from our in vitro study." (PMID 29413957, 2018). "Jerke with co‐authors observed direct MPO transfer from neutrophils to endothelial cells mediated by β2‐integrin upon cell–cell contact followed by MPO‐mediated endothelial dysfunction." (PMID 29364567, 2018). "Leucocyte activity is closely related with this endothelial dysfunction, and it is suggested to have a heavy role in inflammation and CVD risk, especially since MPO is a predominant oxidase within these cells." (PMID 28230726, 2017). "Our study provided data suggesting an interaction between MPO and the mechanisms of endothelial dysfunction." (PMID 28704420, 2017). "Endothelial dysfunction is known to be under the influence of myeloperoxidase (MPO) activity, and its excessive activity can lead to CVD, such as CAD." (PMID 28230726, 2017). "MPO seems to play an important role in endothelial dysfunction, is released from granules of activated leukocytes, and can generate ROS as a system of defense against bacteria." (PMID 27007571, 2016). "Some studies also show that the high concentration of MPO is a diagnostically significant parameter in the prediction of endothelial dysfunction in patients with T2DM." (PMID 27212945, 2016). "We examined vascular contractile and relaxant responses in MPO-deficient (MPO−/−) and wild-type mice to investigate the role for myeloperoxidase in the development of endothelial dysfunction." (PMID 24707472, 2014). "Recently, attention has focused on the enzyme myeloperoxidase (MPO) as a possible contributor to endothelial dysfunction." (PMID 24707472, 2014). "This study was motivated by recent interest in the role of myeloperoxidase in the development of endothelial dysfunction." (PMID 24707472, 2014). "MPO can promote endothelial dysfunction, upregulate inducible nitric oxide synthase and impair lipoprotein function." (PMID 23691142, 2013). "An important consequence of MPO activity is the consumption of NO and thereby induction of endothelial dysfunction." (PMID 21234421, 2010).
endothelial dysfunction (continued). "Increased plasma levels of MPO independently predict endothelial dysfunction and coronary artery disease (CAD), even after adjusting for traditional risk factors or hsCRP." (PMID 20158910, 2010). "Plasma MPO has been accepted to be a good biomarker of endothelial dysfunction and predicted cardiovascular events even in 1,138 apparently healthy subjects in the EPIC-Norfolk Prospective population study." (PMID 20158910, 2010). "However, MPO contributes to endothelial dysfunction primarily through its pro-oxidant activity, generating reactive species such as HOCl that oxidize LDL-C to form oxLDL-C." (PMID 41226326, 2025). "Thus, revelation of MPO’s contribution to endothelial dysfunction “from the outside to the inside” of the vessel wall forms the scope of this work." (PMID 40252642, 2025). "It is currently understood that MPO, through its oxidative activity, not only contributes to endothelial dysfunction but may also serve as a potential biomarker and therapeutic target in this high-risk population." (PMID 41226326, 2025). "Reactive oxidative intermediates, including methylglyoxal (MGO), 4-hydroxynonenal (4-HNE), acrolein, and myeloperoxidase (MPO), mediate signal amplification across tissues and contribute to endothelial dysfunction, inflammasome activation, and neurodegeneration (Section 2.2.2)." (PMID 40782521, 2025). "Existing evidence shows that increased levels of MPO coincide with sustained inflammation and elevated oxLDL-C, which may likely contribute to endothelial dysfunction and subsequent CVDs." (PMID 41226326, 2025). "Surface-bound MPO is subsequently transcytosed through endothelial cells, and deposited in the sub-endothelial space, where it catalyses oxidative reactions that impair NO bioactivity and promote endothelial dysfunction and vasoconstriction." (PMID 39061857, 2024). "In addition to that, MPO and ELA can induce oxidative stress, which can also result in neuronal degeneration, endothelial dysfunction, and loss of SMCs." (PMID 39654759, 2024). "Moreover, MPO-derived oxidative species strongly correlate with endothelial dysfunction, phenotypic switching of vascular smooth muscle cell (VSMCs), and ERK1/2 signaling activation, suggesting a potential link between aneurysm pathogenesis and MPO." (PMID 38509468, 2024). "Moreover, elevated circulating MPO levels in CAD patients independently predict endothelial dysfunction, measured as impaired flow- or acetylcholine-mediated dilation of the brachial artery." (PMID 39061857, 2024). "Elevated levels of MPO in the blood are significant indicators of acute cardiovascular events, atherosclerosis, coronary stenosis, and endothelial dysfunction, furthering the formation of atherosclerotic plaques by promoting lipid peroxidation and negatively impacting left ventricular function." (PMID 39125842, 2024). "Neutrophils could lead to oxidative stress and endothelial dysfunction by releasing large amounts of myeloperoxidase and nicotinamide adenine dinucleotide phosphate oxidase." (PMID 38409069, 2024). "Also, MPO can promote endothelial dysfunction and vasoconstriction by consuming nitric oxide (NO) as a substrate, reducing eNOS activity, and decreasing eNOS Ser1177 phosphorylation." (PMID 39654759, 2024). "The free radical HOCl Is a major product of myeloperoxidase, an enzyme in atherosclerotic lesions that contributes to atherogenic lipoprotein dysfunction, reduced NO bioavailability, endothelial dysfunction, impaired vasoreactivity, and increased atherosclerotic plaque instability." (PMID 37299525, 2023). "MPO-mediated oxidative stress may be one of the mechanistic link betweencomorbidities, inflammation and endothelial dysfunction at the source of HFpEF." (PMID 39077419, 2023). "In addition to findings that MPO promotes endothelial dysfunction and enhances atherosclerotic plaque formation, myocardial infarction also occurs via MPO." (PMID 36902521, 2023).
endothelial dysfunction (continued). "Because MPO can diminish nitric oxide bioavailability that results in endothelial dysfunction, it may be an active mediator of atherogenesis." (PMID 37168278, 2023). "Myeloperoxidase (MPO) is an enzyme that is primarily produced by neutrophils and monocytes and has been implicated in the development of endothelial dysfunction by limiting NO bioavailability through the production of hypochlorous acid (HOCl), a potent oxidant." (PMID 37507899, 2023). "By reducing •NO bioavailability, MPO promotes endothelial dysfunction." (PMID 35624738, 2022). "The elevated MPO may induce oxidative stress and trigger endothelial dysfunction which results in increased blood pressure." (PMID 35740071, 2022). "MPO is able to interact with a wide range of substances producing oxidative species, which may influence endothelial dysfunction." (PMID 36439687, 2022). "A correlation has been established between MPO activity and endothelial dysfunction." (PMID 35624738, 2022). "Under inflammatory conditions, MPO is linked to the RAAS, which aggravates endothelial dysfunction." (PMID 34733402, 2021). "Studies have shown that MPO is abundantly accumulated in the basement membrane under the vascular endothelium in hypercholesterolemia, and it is speculated that it may lead to endothelial dysfunction by the precipitation of NO." (PMID 32190383, 2020). "PIO might inhibit vascular MPO activity and increase NO bioavailability with the net result of reversing endothelial dysfunction." (PMID 32190383, 2020). "MPO has the ability to reduce NO bioavailability through direct oxidization of NO or through the production of NO-consuming substrate radicals, thus contributing to the endothelial dysfunction seen in many vascular pathologies, including TAA." (PMID 33081376, 2020). "High MPO activity indicates NO consumption and the onset of endothelial dysfunction." (PMID 32718122, 2020). "Furthermore, the contribution of rising circulating levels of MPO enzyme to the role of immune cells in endothelial dysfunction is also worthy of mention." (PMID 32796678, 2020). "Interestingly, extracellular MPO can bind to the RBC membrane and is associated with endothelial dysfunction in the context of ischemic heart disease." (PMID 32045382, 2020). "MPO and MPO-derived oxidants have been shown to contribute to the formation of foam cells, endothelial dysfunction and apoptosis, the activation of latent matrix metalloproteinases, and the expression of tissue factor that can promote the development of vulnerable plaque." (PMID 33193322, 2020). "Inhibition of MPO might be a new therapeutic target for AS, especially to limit endothelial dysfunction in vascular inflammation." (PMID 31450823, 2019). "As a substrate for MPO, UA is oxidized to the urate radical and then urate hydroperoxide, suggesting that UA may affect the progression of endothelial dysfunction." (PMID 31636806, 2019). "Rats fed on a high fat diet to establish a hyperlipidemic model, resulted in increased plasma lipids, endothelium-derived myeloperoxidase (MPO) expression, EC senescence and endothelial dysfunction associated with a reduction in glycogen synthase 3 beta (GSK-3β) activity and p-β-catenin." (PMID 30054761, 2018). "Myeloperoxidase-induced endothelial dysfunction could be in part mediated by NO-independent mechanisms, an observation supported by the fact that NO-mediated vasodilation remained unaffected in our study." (PMID 29991814, 2018). "Moreover, the RBC membrane is host to myeloperoxidase (MPO) whose binding induces vascular remodeling and stiffness, and likely contributes to endothelial dysfunction." (PMID 29572498, 2018). "There are several mechanisms by which MPO can promote the atherosclerotic process: oxidation of LDLc; MPO-induced oxidation of HDLc; and consumption and catabolism of endothelial-derived nitric oxide, which can lead to endothelial dysfunction and plaque formation." (PMID 27007571, 2016).